CST3 (cystatin C)
Diseases named in the same sentence as CST3 in open-access papers (continued):
Sharing a sentence is not in itself a finding about the gene and the disease.
sarcoidosis (3 papers, 2013 to 2024). Sarcoidosis is a multisystemic disorder of unknown cause characterized by the formation of immune granulomas in involved organs. "We aimed to identify a correlation between each sarcoidosis blood biomarker and cystatin C (Cys-C) in sarcoidosis patients." (PMID 37448407, 2023). "Protein concentrations of pro-inflammatory cytokines CD14 and Cystatin C have been shown to be elevated in multiple inflammatory disorders and were also elevated in the LDL fraction in sarcoidosis patients compared to healthy controls." (PMID 38627696, 2024).
spinal muscular atrophy (3 papers, 2025 to 2026). A motor neuron disease that affect the muscles, and characterized by muscle weakness and atrophy resulting from progressive degeneration and irreversible loss of the anterior horn cells in the spinal cord (i.e., lower motor neurons) and the brain stem nuclei. "The creatinine to cystatin C ratio (CCR) can be used as a biomarker of muscle mass and strength, but no studies have evaluated whether it can be used as a biomarker to monitor the efficacy of treatment with nusinersen in Chinese adults with 5q-associated spinal muscular atrophy (SMA)." (PMID 40317045, 2025).
urinary tract infection (3 papers, 2021 to 2023). "Cluster 5 and cluster 7 (marked by cystatin C and creatinine) showed a high risk of urinary tract infection (20.4% and 15%, respectively)." (PMID 37248226, 2023).
vitamin D deficiency (3 papers, 2017 to 2021). A nutritional condition produced by a deficiency of VITAMIN D in the diet, insufficient production of vitamin D in the skin, inadequate absorption of vitamin D from the diet, or abnormal conversion of vitamin D to its bioactive metabolites. "The aim of this study is to determine serum cystatin C levels, and the prevalence of vitamin D deficiency and thyroid dysfunction in CKD patients." (PMID 33401560, 2021). "This study was the first double-blind RCT to explore the additional benefit of calcitriol supplement in CKD patients who were receiving ergocalciferol supplementation on proteinuria and kidney function by using serum cystatin C in CKD patients with vitamin D insufficiency/deficiency." (PMID 28088187, 2017).
acute lymphoblastic leukemia (2 papers, 2019 to 2025). Leukemia with an acute onset, characterized by the presence of lymphoblasts in the bone marrow and the peripheral blood. "CST3 and MPO were experimentally demonstrated to exhibit a correlation with acute lymphoblastic leukemia (ALL) or AML." (PMID 40338916, 2025).
acute respiratory distress syndrome (2 papers, 2020 to 2022). Progressive and life-threatening pulmonary distress in the absence of an underlying pulmonary condition, usually following major trauma or surgery. "We hypothesized that elevated levels of plasma cystatin C in patients with acute respiratory distress syndrome (ARDS) would be associated with mortality risk." (PMID 32653023, 2020). "It was shown that cystatin C was significantly higher among those patients with acute respiratory distress syndrome (ARDS) who died and subjects with AKI in the highest quartile of cystatin C had a significantly higher odds of death at 60 d compared to subjects in the lower cystatin C (OR 1.6)." (PMID 35086423, 2022).
acute respiratory failure (2 papers, 2023). Life-threatening respiratory failure that develops rapidly. "The SI based on serum creatinine and cystatin C can predict respiratory failure in patients with AECOPD and either frequent or infrequent exacerbations." (PMID 36774462, 2023).
Anorexia (2 papers, 2020 to 2024). Lack of desire to eat (loss of appetite). "Serum cystatin C levels exhibited a stronger correlation with measured mGFR compared to serum creatinine levels in a study involving individuals with anorexia." (PMID 39125705, 2024).
Arthritis (2 papers, 2011 to 2025). Inflammation of a joint. "Further, a chronic disease profile was observed in the cystatin C-deficient mice compared to wild type controls as there was a significantly longer disease duration and fewer mice recovered from arthritis." (PMID 21443774, 2011). "In relation to arthritis, cystatin C has been found to be the most prominent cystatin in synovial fluid of RA patients and that RA patients have significantly lowered levels of cystatin C in circulation." (PMID 21443774, 2011). "The effect of cystatin C-deficiency was further dissected by testing the inflammatory effector phase of CIA; that is, collagen antibody-induced arthritis model and priming phase, that is, T cell response both in vivo and in vitro." (PMID 21443774, 2011). "Since cystatin C-deficient mice did not have an increased inflammatory effector phase, but had and earlier onset with a higher incidence of arthritis, we wished to investigate the priming phase of CIA." (PMID 21443774, 2011). "Interestingly, when the inflammatory phase of CIA was examined independently from immune priming then cystatin C-deficiency did not enhance the arthritis profile." (PMID 21443774, 2011). "Since cystatin C-deficiency did not alter the inflammatory effector phase and the fact that both cystatin C-deficient and heterozygous mice developed arthritis earlier than the wild type controls, there was an indication that cystatin C-deficiency had an effect on priming the immune response." (PMID 21443774, 2011). "Conversely to the effect of cystatin C-deficiency in CIA, incidence of arthritis and day of arthritis onset were not enhanced in cystatin C-deficient mice in the CAIA model when compared to wild type mice." (PMID 21443774, 2011). "Here, we show that mice lacking cystatin C, develop arthritis at a higher incidence and an earlier onset than wild-type controls." (PMID 21443774, 2011).
Ascites (2 papers, 2023 to 2024). Accumulation of fluid in the peritoneal cavity (between the layers of the peritoneum that lines the abdomen). "Also, studies have demonstrated the superiority of estimating GFR using cystatin C in CLD patients compared to creatinine, and particularly the eGFRcys(ASR) for patients with ascites or significant renal disease." (PMID 37003973, 2023).
astrocytoma (2 papers, 2020 to 2021). "Here, we used an astrocytoma cell line (CCF-STTG1) because of the low levels of endogenous CST3 expression." (PMID 34575849, 2021). "However, His6 immunocytochemistry revealed that the internalization of exogenous recombinant CST3 by an astrocytoma cell culture was higher when the protein was aggregated compared to its monomeric form." (PMID 34575849, 2021).
Auditory hallucination (2 papers, 2024 to 2025). Perception of sounds without auditory stimulus. "For cognitive-related symptoms including auditory hallucinations and other hallucinations, they were associated with higher cystatin C (adjusted β = 0.116–0.239, p < 0.01)." (PMID 39717378, 2024). "Notably, cognitive-related symptoms such as auditory hallucinations were significantly correlated with elevated cystatin C levels." (PMID 40256164, 2025).
benign eye tumors (2 papers, 2013 to 2021). "Tear cystatin C and lactoferrin level, increased in malignant and benign eye tumors, seems to be a perspective for diagnostics in these disorders." (PMID 23984285, 2013). "However, it is impossible to differentiate choroidal melanoma and benign eye tumors according to the level of cystatin C and lactoferrin in eye tear fluids." (PMID 23984285, 2013). "It was hypothesized that cystatin C and lactoferrin could serve as possible biomarkers in the diagnosis of malignant and benign eye tumors." (PMID 23984285, 2013).
Blood Pressure (2 papers, 2022). "Curcumin also lowered adenine-induced high blood pressure, urinary albumin, the inflammatory cytokines interleukins 1 (IL-1) and 6 (IL-6), tumor necrosis factor α (TNF-α), cystatin C (CST3), and adiponectin (ADIPOQ)." (PMID 35910356, 2022).
Brain atrophy (2 papers, 2016 to 2025). Partial or complete wasting (loss) of brain tissue that was once present. "Furthermore, CSF cystatin C predicts rate of brain atrophy, a surrogate marker of neurodegeneration, in established and prodromal AD." (PMID 27845782, 2016).
Cerebral ischemia (2 papers, 2016 to 2020). Restriction of arterial blood supply to the brain associated with insufficient oxygenation to support the metabolic requirements of the tissue. "Therefore, our data indicated that CST3 was functional deficient in Cst3-KO gerbils and CST3 has brain protective effects on cerebral ischemia." (PMID 32733872, 2020). "Cystatin C is a useful biomarker for renal dysfunction and acute cardiac or cerebral ischemia." (PMID 27256246, 2016). "However, whether CST3 is involved in CoW development and brain recovery after cerebral ischemia are not fully understood." (PMID 32733872, 2020).
choroidal melanoma (2 papers, 2013 to 2021). Malignant tumor of melanocytes of the choroid. "In choroidal melanoma, cystatin C level was increased similarly in the tear fluid of both the eyes (with and without tumor) versus control." (PMID 23984285, 2013). "In patients with choroidal melanoma, increased cystatin C concentration was similar in tear fluid of both the eyes." (PMID 23984285, 2013). "The aim is to investigate the role of cystatin C in eye tear fluid and anterior camera of eye locally, and in serum and lactoferrin, revealing anti-tumor activity in eye tumor development (choroidal melanoma)." (PMID 23984285, 2013). "Therefore, in patients with choroidal melanoma cystatin C concentration was elevated in the tear fluid of both the eyes (with tumor and without tumor), whereas in serum similar changes were less prominent." (PMID 23984285, 2013). "Cystatin C concentration is serum was significantly increased (p<0.05) in choroidal melanoma." (PMID 23984285, 2013). "In our study, cystatin C and lactoferrin levels in tear fluid of patients with choroidal melanoma did not relate with the size of the tumor and their localization." (PMID 23984285, 2013).
cognitive diseases (2 papers, 2023 to 2024). "Several hypotheses have been proposed in studies exploring the potential pathogenic role of Cystatin C levels in cognitive diseases." (PMID 37207178, 2023).
congenital heart disease (2 papers, 2016 to 2023). A heart disease that is present at birth. "Similarly, in a prospective study of 59 congenital heart disease-associated PAH patients, cystatin C predicted long-term mortality and clinical worsening." (PMID 37633906, 2023).
diffuse large B-cell lymphoma (2 papers, 2017 to 2024). "Compared by ANOVA or Kruskall Wallis test, *significantly different from control group by Tukey test (p < 0.05) or Mann Whitney test; Abbreviations: DLBCL, diffuse large B- cell lymphoma, CTSS, cathepsin S; Cys C, cystatin C; LDH, lactate dehydrogenase." (PMID 39712508, 2024).
dilated cardiomyopathy (2 papers, 2021 to 2024). Cardiomyopathy which is characterized by dilation and contractile dysfunction of the left and right ventricles. "Our ablation analysis showed that serum cystatin C contributes remarkably for the predictive model, which is a similar finding to those of previous studies on prognosis of dilated cardiomyopathy." (PMID 34422921, 2021).
Fanconi syndrome (2 papers, 2012 to 2013). "Retinol-binding protein (RBP) and cystatin C are examples of LMWP that are found in increased amounts in urine from patients with Fanconi syndrome." (PMID 22883485, 2012). "By contrast, RBP and cystatin C may be better markers of specific forms of proximal tubular dysfunction (such as inherited forms of Fanconi syndrome) or states where proximal tubular dysfunction relates to mitochondrial toxicity – and thus a decrease in energy supply - and not to actual necrosis." (PMID 22883485, 2012). "The current research was initially driven by the report on the decreased CRP level, an important regular of cystatin C level, and evidence of abnormalities of renal tubular function in HNF1A-MODY subjects and a Fanconi’s syndrome in an animal model." (PMID 22350134, 2013).
gingivitis (2 papers, 2017 to 2025). A disorder involving inflammation of the gums; may affect surrounding and supporting structures of the teeth. "Proteomic findings have shown that pregnancy-associated gingivitis involves heightened neutrophil-mediated immune responses and compromised antioxidant defenses, with reduced salivary cystatin C levels predisposing pregnant women to gingival inflammation." (PMID 40366920, 2025).
Hematuria (2 papers, 2024 to 2025). The presence of blood in the urine. "In the training set, patients in the high-risk group exhibited significantly higher levels of BMI, DBP, neutrophil count, serum creatinine, serum cystatin C, cholesterol, triglycerides, hs-CRP, serum C3, UPE and hematuria compared to those in the low-risk group." (PMID 39494280, 2024).
hemorrhagic stroke (2 papers, 2022 to 2024). A stroke caused by a bleed on the brain. "On the other hand, the level of cystatin C correlates with mortality of brain injury patients, including those who suffered ischemic or hemorrhagic stroke." (PMID 38473707, 2024).
hip fracture (2 papers, 2021 to 2024). Traumatic or pathological injury to the hip in which the continuity of either the femoral head, femoral neck, intertrochanteric or subtrochanteric regions is broken. "Recently, the serum creatinine to cystatin C ratio was reported to reflect preoperative and early postoperative walking ability in older patients with hip fracture." (PMID 38347481, 2024).
hippocampal atrophy (2 papers, 2014 to 2016). "High cystatin C (CysC) was associated with higher whole brain atrophy and hippocampal atrophy rates." (PMID 25072324, 2014).
Hyperkalemia (2 papers, 2016 to 2023). An abnormally increased potassium concentration in the blood. "This cohort study assesses the risk of supratherapeutic doses, hyperkalemia, toxic effects, and mortality among adults with cancer with lower serum creatinine–based than cystatin C–based estimated glomerular filtration rate." (PMID 37405775, 2023).
hyperparathyroidism (2 papers, 2022 to 2023). Hyperfunction of the parathyroid glands resulting in the overproduction of parathyroid hormone. "Children with AKD had increased odds for having hypocalcemia while a low Cystatin C defined eGFR was associated with both hypocalcemia and hyperparathyroidism." (PMID 36819194, 2022). "Hyperparathyroidism occurred in 8.7% of children with SCA, was more frequent in children ≥10 years of age (13.2%) and was associated with a marked increase in both Cystatin C and urine NGAL levels." (PMID 36819194, 2022).
hypertensive nephropathy (2 papers, 2017 to 2022). Kidney damage that results from chronically elevated blood pressure; complications include glomerular damage resulting in proteinuria and hematuria. "In the current literature, the prognosis of patients with hypertensive nephropathy is clearly related to clinical indicators such as 24 h urinary protein, SCr, Ccr, cystatin C, and BUN." (PMID 35617324, 2022). "In this study, we conducted a meta-analysis based on 20 RCTs to determine the efficacy of alprostadil in patients with hypertensive nephropathy by using six indicators of hypertensive nephropathy: 24-hour urinary protein, SCr, Ccr, BUN, cystatin C and MAP." (PMID 35617324, 2022).
left ventricular hypertrophy (2 papers, 2018 to 2025). Enlargement of the LEFT VENTRICLE of the heart. "Second, efforts should focus on validating the utility of cystatin C as a predictive biomarker for subclinical cardiac remodeling (e.g., left ventricular hypertrophy) to enhance risk stratification." (PMID 41200622, 2025).
lung squamous cell carcinoma (2 papers, 2024 to 2025). "In lung squamous cell carcinoma, elevated expression of the CST3 gene in tumor-associated fibroblasts, an alternative source of cystatin C, is also associated with reduced responsiveness to immunotherapy and worse clinical outcomes." (PMID 41233352, 2025).
lupus nephritis (2 papers, 2019 to 2020). Glomerulonephritis in the context of systemic lupus erythematosus. "Here, we aimed to compare the clinical effects of mycophenolate mofetil combined with either tacrolimus or with cyclophosphamide on lupus nephritis (LN) and to analyze their influence on the expression of cystatin C and on transforming growth factor-1 (TGF-β1)." (PMID 33206751, 2020).
muscular atrophy (2 papers, 2021 to 2025). The loss of muscle tissue due to inactivity or disease. "We strongly suggest adding serum creatinine (and possibly cystatin C, especially in patients with muscular atrophy) and UPE in the routine diagnostic work-up and follow-up of ATTRv patients." (PMID 34439599, 2021). "Since many PWH experience arthropathies and secondary muscular atrophy, the use of creatinine-based formulas would have been less accurate, further justifying our choice of cystatin C." (PMID 41368294, 2025).
neuroblastoma (2 papers, 2020 to 2021). Neuroblastoma (NB) is the most common solid, extracranial childhood tumor. "In culture conditions, including a neuroblastoma cell culture, CST3 is demonstrated to internalize and localize in the lysosome." (PMID 34575849, 2021). "For instance, CST3 increases neuron viability by inhibiting autophagy and cathepsin B (Cat B) in Cu/Zn-superoxide dismutase (SOD1)-mutant, or cytotoxicity-exposed neuroblastoma cell lines and primary cultured motor neuronal cells." (PMID 32733872, 2020).
Neurogenic bladder (2 papers, 2023 to 2025). A type of bladder dysfunction caused by neurologic damage. "Our study demonstrated that patients with neurogenic bladder exhibit lower serum creatinine concentrations compared to the reference group, alongside higher levels of cystatin C, RBP4, and RBP4 standardized to creatinine excretion in urine." (PMID 40217967, 2025). "According to suggestions from many publications, it is crucial to use more detailed and independent markers, such as cystatin C or a more sensitive GFR ratio calculated from the combined creatinine and cystatin C concentration in patients with neurogenic bladder." (PMID 40217967, 2025).
non-Hodgkin lymphoma (2 papers, 2013 to 2024). Distinct from Hodgkin lymphoma both morphologically and biologically, non-Hodgkin lymphoma (NHL) is characterized by the absence of Reed-Sternberg cells, can occur at any age, and usually presents as a localized or generalized lymphadenopathy associated with fever and weight loss. "Our previous study showed that the level of cystatin C was significantly higher in patients who experienced relapse compared to patients newly diagnosed with non-Hodgkin lymphomas." (PMID 24167744, 2013). "Our recent study showed that patients with B non-Hodgkin lymphomas had significantly higher cystatin C levels compared to healthy controls." (PMID 24167744, 2013).
periodontal disease (2 papers, 2022). "The authors found a significant positive association between serum cystatin C and periodontal disease, concluding that patients with decreased kidney function had a higher probability of periodontal disease." (PMID 35225864, 2022). "A significant positive association between the serum cystatin C and periodontal disease was found in one study." (PMID 35225864, 2022). "Knowledge on the immunomodulatory properties of cystatin C could aid in the design of new therapeutic approaches to improve the treatment of periodontal diseases." (PMID 36312752, 2022). "Knowledge on the antimicrobial and immunomodulatory properties of cystatin C could aid in the design of new therapeutic approaches to facilitate the elimination of this bacterium to improve the treatment of periodontal disease." (PMID 36312752, 2022).